STAT3 (signal transducer and activator of transcription 3)
Diseases named in the same sentence as STAT3 in open-access papers (continued):
Sharing a sentence is not in itself a finding about the gene and the disease.
bladder cancer (continued). "In RC48-treated bladder cancer cells, compensatory activation of the JAK/STAT3 pathways was noted." (PMID 39840049, 2024). "In bladder cancer, ITM2A inhibits bladder cancer by downregulating STAT3 phosphorylation." (PMID 39720726, 2024). "Nonetheless, poor survival of bladder cancer patients correlates with strong nuclear expression of BLCAP, which is impacted by the interaction of BLCAP and Signal Transducer and Activator of Transcription 3 (STAT3) in the JAK/STAT-pathway." (PMID 37055532, 2023). "Moreover, bladder cancer cells overexpressing BCL-xL were refractory to sertindole’s proapoptotic action, arguing that sertindole represses STAT3 to downregulate BCL-xL, culminating in the induction of apoptosis." (PMID 37511611, 2023). "Additionally, osthole blocked the bladder cancer epithelial-mesenchymal transition and promoted bladder cancer cell apoptosis by inhibiting the PI3K-AKT and Janus kinase/signal transducer and activator of transcription (JAK/STAT3) pathways." (PMID 37069622, 2023). "Moreover, reducing the catabolism of tryptophan suppresses IL-6/STAT3/VEGF signaling pathway and attenuates angiogenesis in bladder cancer." (PMID 36559245, 2022). "Our inquiry about how HME suppresses STAT3 activation revealed that SRC appears as the primary STAT3 upstream kinase targeted by HME, as the levels of tyrosine 416-phosphorylated SRC were markedly lowered in all HME-treated bladder cancer cell lines." (PMID 36613579, 2022). "STAT3-induced resistance to doxorubicin has been observed in RCC and bladder cancer." (PMID 36230984, 2022). "The results provide novel insights into the regulation of SENP3/STAT3/PYCR1 pathway, which has key roles in bladder cancer progression and may aid in identifying new biomarkers or targeted therapies for bladder cancer." (PMID 36227136, 2022). "In bladder cancer, the USP24/GSDMB/STAT3 axis is reported to promote tumor proliferation and growth, where USP24 interacts and stabilizes GSDMB, which in turn binds to STAT3, increases its phosphorylation and activates STAT3 signaling." (PMID 35479097, 2022). "STAT3, besides being involved in EMT, participates in bladder cancer angiogenesis." (PMID 36230984, 2022). "Further, STAT3 activated transgenic mice directly developed invasive bladder cancer without going through the intermediate noninvasive stages." (PMID 35068946, 2021). "Even though cucurbitacin E decreased the amount of phosphorylated STAT3 in human bladder cancer cells, it did not alter the levels of STAT3." (PMID 32545187, 2020). "A study investigating bladder cancer showed that AG490 could inhibit cell growth and invasion, as well as induce cell apotosis and cycle arrest by inhibiting the activation of the JAK2/STAT3 signaling pathway." (PMID 32641093, 2020). "In bladder cancer, UCA1 could promote glycolysis by up-regulating hexokinase 2 through both activation of STAT3 and repression of miR-143." (PMID 30918102, 2019). "Thus, in this study, we aim to explore anticancer effect of THP and its molecular mechanisms on bladder cancers after down‐regulating PKM2, focusing on the roles of p‐STAT3 and p‐AMPK." (PMID 29512924, 2018). "As indicated by recent studies, UCA1 activates mTOR by upregulating HK2 and increases glycolysis through both the activation of STAT3 and the repression of miR-143, thereby revealing a novel glucose metabolism regulatory pathway, UCA1-mTOR-STAT3/miR-143/HK2, in bladder cancer cells." (PMID 30134946, 2018). "Phosphorylated STAT3 was constitutively detected in the nucleus of the bladder cancer cell lines T24 and J82 without treatment with metformin." (PMID 26245871, 2015). "Moreover, knockdown of ETK suppresses the activation of STAT3 in two bladder cancer cell lines T24 and UM-UC-3, indicating that ETK functions upstream of STAT3 in bladder cancer cells." (PMID 25849286, 2015).
bladder cancer (continued). "The relationship between IL-6/STAT3 signaling and DNMT1 in bladder cancer was further examined to see whether regulation of IL-6/STAT3 signaling results in changes of DNMT1 expression." (PMID 23637926, 2013). "In addition to STAT3 and AKT pathways which are known to be activated by ETK, we also showed, for the first time, that ETK localizes to mitochondria in bladder cancer cells and thereby regulates ROS production and drug sensitivity." (PMID 21408190, 2011). "Our findings highlight that targeting the STAT3/BCL-xL axis is a promising strategy to eliminate bladder TCC cells and facilitate Cisplatin sensitization, and further support the potential of incorporating Fucoxanthin into Cisplatin-based chemotherapy for treating bladder cancer." (PMID 39997178, 2025). "Interestingly, a previous study in bladder cancer stem cells showed that SUV39H1 maintains the self-renewal of these cells by repressing the transcription factor GATA3, leading to the upregulation of STAT3 and maintaining stemness." (PMID 40059829, 2025). "Its potential mechanism of inducing cisplatin resistance and apoptosis inhibition may be to activate STAT3 by binding to the octamer containing non POU (with highly conserved DNA binding domain) domain, and become a potential new target for bladder cancer treatment." (PMID 37305043, 2023). "It is also worth noting that our discovery about SRC inhibition by HME implies that, besides STAT3, additional signaling pathways downstream of SRC, such as AKT and MAPK, are likely involved in HME’s anticancer mechanisms of action in the context of bladder cancer." (PMID 36613579, 2022). "Moreover, the crucial role of STAT3 blockage in mediating HME’s anti-bladder cancer action was confirmed by the abrogation of HME-elicited cytotoxicity when HME failed to mitigate STAT3 activation." (PMID 36613579, 2022). "Furthermore, HME was proved as a blocker for STAT3 activation, evidenced by the findings that HME inhibits both constitutive and IL-6-induced activation of STAT3, and STAT3 blockage is needed for HME to suppress the viability and clonogenicity of bladder cancer cells." (PMID 36613579, 2022). "Moreover, GSDMB modulated the glycolysis by up-regulating the expression of HK2 in bladder cancer cells, suggesting that GSDMB might be involved in regulating the glucose metabolism of bladder cancer cells through STAT3-related signaling pathways." (PMID 34326684, 2021). "Furthermore, we found that STAT3 could bind to the promoter of IGFBP3, indicating that STAT3 acted as a transcription factor to initiate the transcription of IGFBP3 in bladder cancer cells." (PMID 34326684, 2021). "The report also demonstrated that Twist1 and STAT3 were crucial for the pirarubicin chemoresistance and tumor recurrence in non-muscle invasion bladder cancer, and this result could be reversed via DAB2 interactive protein." (PMID 32872659, 2020). "Thus, we speculate that the role of miR-153 in bladder cancer angiogenesis is to target IDO1 expression and regulate IL6/STAT3/VEGF signaling." (PMID 31355138, 2019). "In addition, using preclinical models of murine bladder cancer, we demonstrated that repeated intraperitoneal injections of DAB-1 (150 μM) inhibited tumor growth by 90% and stopped the formation of pulmonary metastasis, likely by inhibiting the TNFα/NFκB and IL6/STAT3 signaling pathways." (PMID 40807456, 2025). "Next, we set out to assess whether STAT3 inhibition/TLR9 stimulation using CpG-STAT3ASO will prove effective alone or together with immune checkpoint blockade against genitourinary cancers, such as Renca and MB49 tumors, two commonly used models of mouse kidney and bladder cancers." (PMID 38259453, 2023). "Hence, STAT3 activation is crucial for inducing PD-L1 expression in tumor cells and inhibition of STAT3 activity may inhibit the CXCL9/CXCR3 signaling-induced PD-L1 expression, benefiting bladder cancer patients." (PMID 33407095, 2021).
bladder cancer (continued). "We found that down-regulation of ETK in bladder cancer cells attenuated STAT3 and AKT activity whereas exogenous overexpression of ETK had opposite effects, suggesting that deregulation of ETK may attribute to the elevated activity of STAT3 and AKT frequently detected in bladder cancer." (PMID 21408190, 2011). "In addition, in multiple bladder cancer datasets (including TCGA-BLCA, GSE13507, GSE48075, and GSE32894), we observed a negative correlation between STAT3 and ERBB2 in mRNA levels." (PMID 39840049, 2024).
liver fibrosis (204 papers, 2011 to 2026). "For example, blocking IL‐6 via disrupting the HLF/IL‐6/STAT3 circuit has been associated with reduced HSCs induction and improved liver function in experimental models of liver fibrosis." (PMID 41487942, 2026). "In a preclinical study of a mouse model of liver fibrosis induced by CCl4, exosomes containing miR–181–5p were shown to increase autophagy and decrease liver fibrosis caused by TGF-β1 by blocking the STAT3/Bcl-2/Beclin 1 pathway in HSCs." (PMID 41244150, 2025). "Saikosaponin b1 attenuates liver fibrosis by competitively disrupting the interaction between signal transducer and activator of transcription 3 (STAT3) and glioma‐associated oncogene‐1 (Gli1) in the activated hepatic stellate cells (HSCs)." (PMID 41163803, 2025). "STAT3 was specifically knocked down in mice liver through adeno‐associated virus (AAV) 8‐ApoE‐shSTAT3 to further determine if Ssb1 attenuates liver fibrosis depending on STAT3." (PMID 41163803, 2025). "PZW mitigated hepatic fibrosis in association with IL-6/JAK2/STAT3 and TGF-β/Smad2/3 signaling pathway inhibition favoring MMP1/TIMP-1 ratio that attenuated collagen deposition and promoted collagen degradation." (PMID 41293246, 2025). "Deficiencies in STAT3 DNA-binding were reported to be mediated by increasing the expression of Pias3 in liver fibrosis." (PMID 38751599, 2024). "TXNDC5 promotes hepatic stellate cell activity and ECM through JNK and STAT3 signaling, thereby causing liver fibrosis (LF)." (PMID 38629066, 2024). "Nevertheless, persistent activation of STAT3 in the liver has been associated with the development and progression of apoptosis and fibrosis in the liver fibrosis." (PMID 38281933, 2024). "Activation and over-expression of STAT3 have been implicated in many cancers including solid blood tumors and other diseases such as liver fibrosis and rheumatoid arthritis." (PMID 37978263, 2023). "JQ-1 from the SEA relieves liver fibrosis caused by S. japonicum infections by inhibiting JAK2/STAT3 signaling." (PMID 36986363, 2023). "Recently, ROCK2 has been implicated in the regulation of pro-inflammatory pathogenic macrophages differentiation via STAT3/cofilin signaling pathways in the context of liver fibrosis in mice." (PMID 37980369, 2023). "In conclusion, the current study found that PGC-1α deficiency deteriorated the I/R-induced liver fibrosis by enhancing the IL-6/JAK2/STAT3 signaling and M2-type macrophage polarization." (PMID 37679346, 2023). "Researchers have documented that STAT3 is closely related to the occurrence and development of liver fibrosis caused by various factors." (PMID 37480105, 2023). "JQ-1 is a small-molecule bromodomain inhibitor that relieves liver fibrosis caused by Schistosoma japonicum infections by inhibiting JAK2/STAT3 signaling." (PMID 36389166, 2022). "Accumulating evidence suggests that STAT3 is closely associated with the occurrence and development of liver fibrosis caused by various factors." (PMID 36588728, 2022). "Recently, STAT3 has been documented to be closely linked to the existence and progress of liver fibrosis, triggered by numerous factors." (PMID 35337166, 2022). "The JAK/STAT3 signaling pathway has been reported to be implicated in the fibrosis of diseases, such as cardiac fibrosis, subepithelial fibrosis, and hepatic fibrosis." (PMID 34784837, 2021). "Loss of hepatic STAT5 increased TGF-β and STAT3 activation in mice upon CCl4 treatment, which resulted in exacerbated liver fibrosis." (PMID 32708044, 2020). "The STAT3 is a transcription factor associated with the proliferation and activation of HSCs, and thus it can contribute to hepatic fibrosis." (PMID 33261209, 2020). "On the other hand, repression of STAT3 expression was found to exacerbate liver inflammation in interleukin-10-deficient mice and accelerate hepatic fibrosis during cholestasis." (PMID 29615085, 2018).
liver fibrosis (continued). "Several secreted or intracellular factors related to cell regulation (“signaling pathway”) were also upregulated, some of them (Trib3, CTGF/CCN2, Egr1, Stat3...) having been linked to inflammation, tissue repair, liver fibrosis and TGFβ signaling." (PMID 26446156, 2016). "In a previous study, AMPK activation attenuating leptin-mediated hepatic fibrosis is associated with inhibition of STAT3 activation." (PMID 25188319, 2014). "While the EGFR/JAK1/STAT3 pathway is associated with fibrosis in various organs, its role in liver fibrosis remains unclear." (PMID 41181146, 2025). "Moreover, treatment of HCC with small molecule STAT3 inhibitor C188‐9 conferred resistance to MASH‐associated liver fibrosis." (PMID 40066227, 2025). "In addition, the amelioration of CCl4-induced hepatic fibrosis by cucurbitacin-B is also associated with the blockade of STAT3 phosphorylation." (PMID 36671504, 2023). "Furthermore, there is evidence that the TGF-β1/STAT3 pathway is an important inflammatory pathway which causes liver fibrosis and cirrhosis." (PMID 35639503, 2022). "Therefore, the current work aimed at investigating the potential antifibrotic effect of lycorine against thioacetamide-induced liver fibrosis in rats, along with elucidating the possible causal mechanisms with respect to the STAT3 pathway." (PMID 35337166, 2022). "STAT3 is closely associated with the pathogenesis of liver fibrosis." (PMID 35915850, 2022). "Next, we investigated whether the inhibitory effects of kahweol on hepatic fibrosis were mediated via STAT3, because hepatic fibrosis is associated with STAT3 phosphorylation." (PMID 29152065, 2017). "And in a murine model of hepatic fibrosis induced by CCL4, increased EGFR expression and STAT3 activation in hepatic macrophages were positively associated with M1 macrophage infiltration and collagen deposition." (PMID 41181146, 2025). "In the schistosome-induced mouse liver fibrosis model, liposomal IL-22 improved fibrosis via the miR-let7a/STAT3 signaling pathway." (PMID 39995661, 2025). "In conclusion, blocking Type I IFN signaling significantly alleviates liver fibrosis by modulating macrophage-derived STAT3 signaling, promoting anti-inflammatory responses, and supporting tissue repair and regeneration." (PMID 40260261, 2025). "In the liver, inhibiting STAT3 has been shown to prevent MASLD-induced hepatic fibrosis and protect the liver from lipotoxicity." (PMID 41415839, 2025). "Activation of the EGFR and JAK1/STAT3 signaling pathways has been shown to promote pro-inflammatory polarization in macrophages, thereby accelerating hepatic fibrosis through mechanisms such as inflammation regulation, oxidative stress, and apoptosis." (PMID 41181146, 2025). "Our findings indicate that macrophage-derived STAT-3 signaling protects against liver fibrosis through type I IFNs." (PMID 40260261, 2025). "A recent study demonstrated that JAK2/STAT3 functions downstream of the HSP27 pathway in liver fibrosis." (PMID 40230054, 2025). "In our experiments, PZH administration significantly reduced the expression of EGFR, JAK1, and STAT3 in liver tissues compared to liver fibrosis mice." (PMID 41181146, 2025). "Collectively, our results suggest that PZH exerts pharmacological effects on liver fibrosis by modulating the EGFR/JAK1/STAT3 signaling pathway." (PMID 41181146, 2025). "This is particularly relevant in hepatic fibrosis, where excessive STAT3 activation has been shown to exacerbate inflammasome activity and hepatocyte pyroptosis." (PMID 41181146, 2025). "IL-22 activated the STAT3 signaling pathway by binding to its receptor, which in turn induced senescence in HSCs and attenuated liver fibrosis." (PMID 39995661, 2025). "Collectively, these results suggest that Ssb1 inhibited STAT3 activation in the HSCs and attenuated liver fibrosis in a STAT3‐dependent manner." (PMID 41163803, 2025).